RNU6-1085P (RNA, U6 small nuclear 1085, pseudogene)
Gene: Small nuclear RNA gene on chromosome 7 (35,930,158 to 35,930,264, reverse strand). Ensembl gene ENSG00000200446.
Homologues: Orthologues: chimpanzee U6 (96% identical). Paralogues in human: RNU6-326P (96% identical), RNU6-1335P (95% identical), RNU6-20P (90% identical), RNU6-812P (90% identical), RNU6-16P (89% identical), RNU6-211P (89% identical), RNU6-25P (89% identical), RNU6-35P (89% identical), RNU6-1 (88% identical), RNU6-11P (88% identical), RNU6-1316P (88% identical), RNU6-144P (88% identical), and 1287 more.